CDKN1A (cyclin dependent kinase inhibitor 1A)
Description:
Plays an important role in controlling cell cycle progression and DNA damage-induced G2 arrest. Binds to and inhibits cyclin-dependent kinase activity, preventing phosphorylation of critical cyclin-dependent kinase substrates and blocking cell cycle progression. Functions in the nuclear localization and assembly of cyclin D-CDK4 complex and promotes its kinase activity towards RB1. At higher stoichiometric ratios, inhibits the kinase activity of the cyclin D-CDK4 complex. Inhibits DNA synthesis by DNA polymerase delta by competing with POLD3 for PCNA binding. Negatively regulates the CDK4- and CDK6-driven phosphorylation of RB1 in keratinocytes, thereby resulting in the release of E2F1 and subsequent transcription of E2F1-driven G1/S phase promoting genes (By similarity).
Synonyms: MDA-6; CAP20; CDKN1; CIP1; SDI1; WAF1; P21; p21CIP1; p21Cip1/Waf1
Tractability: Small molecule: it belongs to a druggable protein family. PROTAC: UniProt records ubiquitination sites on it; ubiquitination databases record sites on it; a small molecule that binds it is known.
Target class: Other cytosolic protein
Gene: Protein-coding gene on chromosome 6 (36,676,441 to 36,687,397, forward strand). Ensembl gene ENSG00000124762.
Subcellular location: Cytoplasm; Nucleus
Subcellular location (Human Protein Atlas): Nuclear bodies; Nucleoplasm
Pathways (Reactome):
Cell Cycle: Cyclin A:Cdk2-associated events at S phase entry; Cyclin D associated events in G1; Cyclin E associated events during G1/S transition; SCF(Skp2)-mediated degradation of p27/p21; The role of GTSE1 in G2/M progression after G2 checkpoint; Transcriptional activation of cell cycle inhibitor p21
Disease: Constitutive Signaling by AKT1 E17K in Cancer; Defective binding of RB1 mutants to E2F1,(E2F2, E2F3); STAT5 activation downstream of FLT3 ITD mutants; Signaling by ALK fusions and activated point mutants; Signaling by FLT3 fusion proteins
Gene expression (Transcription): FOXO-mediated transcription of cell cycle genes; RUNX3 regulates CDKN1A transcription; TFAP2 (AP-2) family regulates transcription of cell cycle factors; Transcriptional regulation by RUNX2
Cellular responses to stimuli: DNA Damage/Telomere Stress Induced Senescence; Formation of Senescence-Associated Heterochromatin Foci (SAHF); KEAP1-NFE2L2 pathway; Senescence-Associated Secretory Phenotype (SASP)
Developmental Biology: Regulation of MITF-M-dependent genes involved in cell cycle and proliferation; Transcriptional regulation of granulopoiesis
Immune System: Interleukin-4 and Interleukin-13 signaling
Metabolism of proteins: Neddylation
Signal Transduction: AKT phosphorylates targets in the cytosol
Gene Ontology:
Molecular function: cyclin-dependent protein serine/threonine kinase inhibitor activity; molecular function activator activity; molecular function inhibitor activity; protein binding; protein kinase binding; protein sequestering activity; protein serine/threonine kinase binding; protein-containing complex binding; ubiquitin protein ligase binding; cyclin binding; protein kinase inhibitor activity
Biological process: cellular response to amino acid starvation; cellular response to cell-matrix adhesion; cellular response to ionizing radiation; cellular senescence; DNA damage response; import into nucleus; mitotic G1 DNA damage checkpoint signaling; mitotic G2 DNA damage checkpoint signaling; negative regulation of cell growth; negative regulation of cell population proliferation; negative regulation of DNA biosynthetic process; negative regulation of G1/S transition of mitotic cell cycle; negative regulation of protein phosphorylation; negative regulation of vascular associated smooth muscle cell proliferation; positive regulation of fibroblast proliferation; positive regulation of protein kinase activity; positive regulation of protein phosphorylation; positive regulation of reactive oxygen species metabolic process; Ras protein signal transduction; regulation of cell cycle; regulation of cell cycle G1/S phase transition; regulation of G1/S transition of mitotic cell cycle; regulation of G2/M transition of mitotic cell cycle; cellular response to UV-B; and 15 more
Cellular component: cyclin-dependent protein kinase holoenzyme complex; cytoplasm; nuclear body; nucleolus; nucleoplasm; nucleus; PCNA-p21 complex; protein-containing complex; cytosol
Genetic constraint (gnomAD): Loss-of-function variants: 14 observed, 14.63 expected, observed/expected ratio (o/e) 0.96, 90% interval 0.63 to 1.49. The upper end of that interval is the gene's LOEUF score, 1.49, which puts it in group 6 of 6, group 1 being the genes least tolerant of losing a copy. Missense variants: 203 observed, 238.02 expected, observed/expected ratio (o/e) 0.85, 90% interval 0.76 to 0.96. Synonymous variants: 92 observed, 97.07 expected, observed/expected ratio (o/e) 0.95, 90% interval 0.8 to 1.13.
Homologues: Orthologues: chimpanzee CDKN1A (100% identical), macaque CDKN1A (97% identical), dog CDKN1A (83% identical), pig CDKN1A (82% identical), guinea pig CDKN1A (77% identical), mouse Cdkn1a (77% identical), rat Cdkn1a (75% identical), zebrafish cdkn1a (29% identical), tropical clawed frog cdkn1a (29% identical). Paralogues in human: CDKN1C (24% identical), CDKN1B (24% identical).
Diseases named in the same sentence as CDKN1A in open-access papers:
CDKN1A is named in the same sentence as 369 diseases in open-access papers, as found by Europe PMC text mining. Sharing a sentence is not in itself a finding about the gene and the disease. The quoted sentences say what the papers report.
breast carcinoma (194 papers, 2002 to 2026). "We transduced SK-LU-1 lung adenocarcinoma and MDA-MB-231 breast cancer cells with doxycycline (dox)-inducible and V5-tagged constructs encoding either CDKN1A or a luciferase control." (PMID 39870664, 2025). "Meanwhile, elevated levels of their downstream target genes (ESR1 and CDKN1A) were associated with poor prognosis of breast cancer patients." (PMID 38254989, 2024). "Its family members (CDKN1A/p21CIP1 and B/p27KIP1) have been implicated in breast cancer, but information about CDKN1C's role is limited." (PMID 18325103, 2008). "Moreover, in breast cancer, the loss of CDKN1A expression greatly reduces the sensitivity of cell cycle-related drugs such as CDK4/6 inhibitors and paclitaxel." (PMID 39268503, 2024). "Along this line, it was shown that 50% of CRC cases show a loss of CDKN1A expression and this correlated with CIN, but not with MIN/MSI, which is in agreement with our results from colorectal and breast cancer showing that loss of CDKN1A correlates with the CIN status of the cancer samples." (PMID 33168930, 2021). "However, in breast cancer cells, the expression of CDKN1A mRNA was upregulated by ZMYND8 loss, which suggests ZMYND8 depletion can increase the p21, which is an inhibitor of cell-cycle progression." (PMID 33670804, 2021). "RUSC1-AS1 promotes the proliferation of breast cancer by inhibiting KLF2 and CDKN1A, which may serve as a potential hallmark for breast cancer." (PMID 32793475, 2020). "Knockdown of USP30-AS1 reduced breast cancer cell proliferation and tumor growth by modulating the expression of CDKN1A/p21, c-Myc, and cyclin D1." (PMID 41492473, 2026). "It has been shown that estradiol-induced PIM-1 overexpression in breast cancer leads to the phosphorylation of key proteins, which in turn suppresses the expression of cell cycle inhibitors (CDKN1A and CDKN2B)." (PMID 40565356, 2025). "We also found evidence of colocalization of whole-blood CDKN1A expression, CAD, and breast cancer susceptibility at the CDKN1A locus and that whole-blood CDKN1A expression increased the risk of CAD but lowered the risk of breast cancer." (PMID 40874306, 2025). "The interplay between EZH2 and other cell cycle targets (e.g., AURKA, CHEK1, CDKN1A) has also been reported in other contexts such as breast cancer, melanoma, non-Hodgkin’s lymphoma, T-cell acute lymphoblastic leukemia." (PMID 38405800, 2024). "In ER+ breast cancer, ESR1 mutations have become a key mechanism of resistance to endocrine therapy; therefore, CDKN1A becomes a very promising target for cancer treatment." (PMID 38254989, 2024). "We next analyzed the associations between FGF2 and FGFR1 gene expression levels and the expression of CDKN1A or CCND1 in the tumor transcriptomes of 601 ER + breast cancer patients from the Cancer Genome Atlas (TCGA)." (PMID 38553760, 2024). "In breast cancer patients, we observe a reduction in CDKN1A/p21 expression when compared to normal samples, although there is some variation among patients." (PMID 38139316, 2023). "TFAP2 suppresses tumor proliferation mediated through P21 (also known as CDKN1A, cyclin dependent kinase inhibitor 1A) regulation in several types of tumors, such as melanoma, breast cancer, colorectal cancer, pancreatic cancer and neuroblastoma." (PMID 37291585, 2023). "The “Go-or-Grow” phenotypic switch in cancer was modeled in vivo by knocking out the p21CIP1-coding gene CDKN1A in the polyoma virus middle T mammary tumour model." (PMID 37259089, 2023).
breast carcinoma (continued). "With the exception of SKP2 and CDKN1A, expression of each of these genes was significantly elevated in ER+ breast cancers with PRR11 copy number gain/amplification in the METABRIC and TCGA dataset." (PMID 33127913, 2020). "Chemotherapy-driven increases in the CDKN1A/PTN/PTPRZ1 axis activate the NF-κB pathway in breast cancer cells." (PMID 30497491, 2018). "To understand the upstream mechanism of chemotherapy-driven increases in PTN expression in breast cancer, we found that the nucleoprotein CDKN1A exhibited the most upregulated expression after treatment with Dox via microarray analysis." (PMID 30497491, 2018). "We also found that the expression of PTN in breast cancer cells which were undergoing Dox treatment was significantly decreased when CDKN1A was knockdown." (PMID 30497491, 2018). "TFAP4 has been shown to repress the cell cycle checkpoint gene CDKN1A in a breast cancer cell line MCF7." (PMID 29880876, 2018). "In agreement with the cell blockage induced by the silencing of SETD6, all breast carcinoma cell lines investigated expressed increased levels of CDKN1A in response to reduced expression of SETD6." (PMID 24751716, 2014). "TFAP2C has been shown to regulate the cyclin-dependent kinase inhibitor (p21CIP1/CDKN1A) in breast cancer cell lines, but data are controversial." (PMID 21779369, 2011). "CDKN1A and B play important and complex roles in breast cancer, but knowledge of CDKN1C's role is limited." (PMID 18325103, 2008). "We then focused on breast cancer samples with PIK3CA mutations and observed that PIK3CA-mutant patients with high CDKN1A expression were associated with poorer overall patients survival compared to patients with mutant PI3K but lower CDKN1A levels." (PMID 38273040, 2024). "Similarly, depletion of the stem cell marker Musashi-1 (MSI1) leads to the upregulation of CDKN1A/p21 and increased apoptosis in breast cancer cells." (PMID 38139316, 2023). "Moreover, the cytoplasmic translocation of CDKN1A/p21 in SUM159 breast cancer cells has been found to enhance chemoresistance." (PMID 38139316, 2023).
breast carcinoma (continued). "PVT1 has been identified as a prognostic biomarker and played a critical role in the development of pancreatic ductal adenocarcinoma via triggering cytoprotective autophagy, and it affected EMT and cell proliferation and migration via modulating CDKN1A expression in breast cancer." (PMID 33868366, 2021). "Together, these findings suggest that the benefit of inhibiting BCL6 in combination with paclitaxel in breast cancer could be at least in part explained by the release of CDKN1A suppression." (PMID 33932086, 2021). "Knockdown of RUSC1-AS1 via inhibiting cell cycle progression through the KLF2/CDKN1A axis could induce apoptosis in breast cancer cells." (PMID 33330110, 2020). "However, other studies reported that CDKN1A/p21 expression promoted breast cancer and mediated drug resistance, and clinical studies have indicated that high p21 expression was correlated with poor prognosis of gastric and esophageal cancers." (PMID 30701134, 2019). "In addition, both normal murine vascular smooth muscle cells and neoplastic human breast cancer cells were induced to undergo partial arrest at G2/M and showed increased expression of CDKN1A upon simulated μG." (PMID 31561588, 2019). "In addition to estrogen signaling and resistance to therapy, 7 of the identified genes have been previously associated with cell cycle regulation (CCND1, CDKN1A, CDKN1B, and CDKN2A) and breast cancer aggressiveness (CLDN7 and DLC1)." (PMID 22616718, 2012). "In BC, CDKN1A/p21 is induced by the Akt pathway, particularly in HER-2/neu-overexpressing cells, results in cytoplasmic localization in breast cancer cell lines." (PMID 39469631, 2024). "Additionally, we observed downregulation of genes such as POLR1A, POLR1D, POLR1E, TAF1B, LAMP1, and CDKN1A in response to AQ treatment demonstrating the role of AQ in regulating RNA polymerase subunits and effect on overall gene transcription in breast cancer." (PMID 36232751, 2022). "Although there is no direct evidence to clarify the mechanism of chemotherapy-driven increases in CDKN1A expression, chemotherapy may inhibit the hypermethylation of the CDKN1A promoter region, which contributes to the rescue of CDKN1A from transcriptional inactivation in breast cancer." (PMID 30497491, 2018). "To assess the influence of assay design on reproducibility, we prepared three additional sets targeting CDKN1A and IGF-1 in duplex reactions, using diluted breast cancer cDNA." (PMID 40869117, 2025). "Here, we found that Doxo and Abe upregulated the expression of CDKN1A and CDKN2A, resulting in cellular senescence in breast cancer cells, which is consistent with previous reports." (PMID 37993606, 2023). "It promotes the proliferation of breast cancer cells by epigenetic silence of KLF2 and CDKN1A, and is also involved in hepatocellular carcinoma by modulating Notch signaling through its interaction with miR-7-5p." (PMID 36290414, 2022).